METTL3 (methyltransferase 3, N6-adenosine-methyltransferase complex catalytic subunit)
Diseases named in the same sentence as METTL3 in open-access papers (continued):
Sharing a sentence is not in itself a finding about the gene and the disease.
renal cell carcinoma (continued). "For example, lower METTL3 expression was detected in renal cell carcinoma (RCC) tissues, suggesting that higher METTL3 expression may predict a better prognosis for RCC patients, possibly due to the inhibition of tumor growth by promoting cell cycle arrest in the G1 phase." (PMID 38166703, 2024). "In contrast, METTL3 has demonstrated a tumour suppressive role in other cancer types such as renal cell carcinoma (RCC) and colorectal cancer." (PMID 36733939, 2022). "Although some data have shown that METTL3 plays an essential role in the progression of clear-cell renal cell carcinoma RCC (ccRCC), the detailed mechanism still remains largely undetermined." (PMID 35794583, 2022). "Inverse correlation of METTL3 expression and renal cell carcinoma (RCC) progression and development was reported in another study." (PMID 33814008, 2021). "Furthermore, the observation that increased phosphorylation levels of PI3K/AKT/mTOR due to METTL3 knockdown suggests that these METTL3-mediated pathways may also be involved in renal cell carcinoma progression." (PMID 32404927, 2020). "Moreover, knockdown of METTL3 appreciably promoted cell proliferation, migration, and invasion and induced G0/G1 arrest, suggesting that METTL3 may act as a tumor suppressor in renal cell carcinoma." (PMID 31921660, 2019). "METTL3 has been shown to play a significant oncogenic role in multiple cancers, including bladder, pancreatic, hepatic, gastric, colorectal, and renal cell carcinoma (RCC)." (PMID 40572597, 2025). "The clinical data showed that the expression of METTL3 and ZEB2 in RFs was significantly greater than that in adjacent normal tissues from renal cell carcinoma patients." (PMID 39059495, 2024). "METTL3, acting as a “writer,” was found to be a methylation regulator inhibiting the expression of HHLA2 in renal cell carcinoma." (PMID 36765416, 2023). "Lower expression of METTL3 was detected in renal cell carcinoma (RCC) tissues, and higher expression of METTL3 might predict better survival outcome of RCC patients." (PMID 35399719, 2022). "However, METTL3 has also been identified as a tumor suppressor in renal cell carcinoma (RCC) and inhibits the proliferation, migration, and progression of cancer." (PMID 36371254, 2022). "Although the effects of METTL3 are mechanistically similar to those in GC and LCA in terms of the EMT and PI3K-Akt-mTOR pathways, in renal cell carcinoma (RCC), knocking down METTL3 significantly promoted cell proliferation, migration and invasion." (PMID 33431045, 2021). "Pathway analysis showed that multiple cancers and related signaling pathways (such as renal cell carcinoma, thyroid cancer and HIF-signaling pathway) correlated with METTL3-mediated m6A modification." (PMID 31607270, 2019). "Further study has shown that METTL3, along with METTL4, METTL14, NCBP1, and WTAP, may interact to impact cell cycle, renal cell carcinoma, and pathways that are included in cancer and hence may influence CRC growth." (PMID 40177651, 2025). "METTL3 protein was undetectable in the non-tumorous adjacent normal kidney tissue from patients with renal cell carcinoma." (PMID 38904026, 2024). "Furthermore, in renal cell carcinoma (RCC), decreased Mettl3 expression resulted in increased proliferation through induction of the PI3K/AKT/mTOR pathway." (PMID 35350378, 2022). "However, in renal cell carcinoma (RCC), higher expression of METTL3 may predict better patients’ survival outcomes possibly by promoting cell cycle arrest in the G1 phase and thus suppressing tumor growth." (PMID 38966069, 2024).
endometrial cancer (45 papers, 2019 to 2026). Primary or metastatic malignant neoplasm involving the endometrium (mucous membrane that lines the endometrial cavity). "In endometrial cancer patients, most of them exhibit reductions in m6A methylation that are probably due to either reduced expression of METTL3 or METTL14 R298P mutation." (PMID 39872957, 2023). "R298 of METTL14 is located close to the METTL3/METTL14 junction and catalytic site, and this mutation is frequently found in human endometrial cancer, suggesting the biological relevance of a mutation in the inactive activator of the METTL3/METTL14 complex." (PMID 36889590, 2023). "The differences were likely due to a METTL14 mutation or reduced expression of METTL3, which promotes cell proliferation and the tumorigenicity of endometrial cancer through the activation of AKT signaling pathway." (PMID 35280730, 2022). "In endometrial cancer, 70% of tumors result in reduced m6A levels through the downregulation of METTL3 expression or METTL14 mutation." (PMID 36360287, 2022). "Increased Akt activation with decreased m6A methylation of the target transcripts due to mutation in METTL14 or METTL3 downregulation contributed to endometrial cancer progression." (PMID 33814008, 2021). "For example, endometrial cancer is associated with a reduced level of m6A mRNA methylation because of decreased expression of METTL3 and METTL14 and reduced m6A methylation promotes the proliferation of endometrial cancer cell." (PMID 34149801, 2021). "For example, decreased METTL3 expression or METTL14 mutation in endometrial cancer reduces the m6A modification of AKT pathway-related genes, resulting in the activation of the AKT signaling pathway and contributing to tumorigenesis." (PMID 31722709, 2019). "By contrast, in endometrial cancer, METTL3 safeguards NLRC5 via a YTHDF2-dependent mechanism, maintaining MHC-I transcriptional programs and associating with greater CD8+ T-cell presence and tumor control." (PMID 41280938, 2025). "Mettl3 is involved in the progression of several tumors and mainly exhibits oncogene property, but showed anti-tumor function in endometrial cancer by targeting the AKT pathway." (PMID 40765834, 2025). "In contrast, METTL3 can act as a tumour suppressor in papillary thyroid cancer or endometrial cancer." (PMID 39095708, 2024). "For instance, METTL3 acts as an apoptotic driver in LUAD 173 whereas WTAP serves as a suppressor in endometrial cancer." (PMID 37063421, 2023). "METTL3 was shown to inhibit cellular proliferation in endometrial cancer, as METTL3-mediated m6A promoted the translation of PHLPP2, a negative regulator of pro-proliferative AKT signaling." (PMID 35350378, 2022). "Reductions in m6A methylation induced by decreased METTL3 and mutation in METTL14 activate the phosphoinositide 3 kinase/protein kinase B (PI3K/AKT) pathway, promoting proliferation and tumorigenicity of endometrial cancer." (PMID 34149936, 2021). "For example, in endometrial cancer, 70% of tumours exhibit a reduction in m6A levels, either through METTL14 mutations or downregulation of METTL3 expression." (PMID 33461542, 2021). "For example, most studies support the oncogenic role of METTL3 in human cancers 13; however, METTL3 exerts a tumor-suppressive role in endometrial cancer." (PMID 34239358, 2021). "Recently, decreased m6A RNA methylation level caused by METTL14 R298 mutation or decreased METTL3 expression has been reported to promote tumorigenicity and cell proliferation via activation of AKT signaling pathway in endometrial cancer." (PMID 34149936, 2021). "METTL3 was also observed to be significantly decreased in endometrial cancer tissues compared to the adjacent normal tissues." (PMID 32733931, 2020). "METTL3 expression was significantly decreased in the endometrium of adenomyosis patients with reduced total m6A levels, similar to those in endometrial cancer." (PMID 32719721, 2020).
endometrial cancer (continued). "In endometrial cancer, METTL14 mutation or METTL3 down-regulation leads to a decrease of mTOR m6A levels, which is a regulator of oncogene AKT." (PMID 32998774, 2020). "In endometrial cancer, METTL3 and METTL14 exhibit a tumor suppressor function." (PMID 38343637, 2024). "Likewise, in endometrial cancer, METTL3 contributes to the decay of transcripts such as PHLPP2 and mTORC2 via YTHDF2, inhibiting cancer cell proliferation." (PMID 38966069, 2024). "Therefore, METTL3 mainly plays a tumor suppressor role in endometrial cancer and there are limited studies on the mechanism so far." (PMID 39872957, 2023). "Interestingly, METTL3 promotes tumor progression by regulating the translation of oncoproteins in different human cancers such as liver, lung and endometrial cancer." (PMID 36556377, 2022). "The loss of METTL3 and METTL14 complexes can upregulate the expression of AKT pathway members and lead to increased cell proliferation, which in turn exhibits tumor suppressor functions in endometrial cancer." (PMID 36360287, 2022). "METTL3-METTL14 complex loss leads to increased cell proliferation by upregulating the expression of members of the AKT pathway, and thus, showing a tumour suppressor function in endometrial cancer." (PMID 33461542, 2021). "Overexpression of METTL3 promotes m6A modification of NLRC5, increases the proportion of CD8+ T cells, and inhibits the progression of endometrial cancer." (PMID 39726589, 2024). "For instance, in lung cancer the oncogenic role of METTL3 promotes the expression of EGFR, whereas in endometrial cancer, it activates the AKT pathway." (PMID 36556377, 2022). "On the contrary, reduced METTL3 expression followed by reductions in m6A methylation increased AKT activity and thus promoted the proliferation and tumorigenesis of endometrial cancer." (PMID 34149801, 2021). "Decreases in METTL3 regulate AKT activities and promote the proliferation and tumorigenicity of endometrial cancer, and m6A methylation regulates AKT pathways." (PMID 33932138, 2021). "Mechanistically, reduced METTL3 could lead to activation of the AKT pathway, which promoted rapid proliferation of endometrial cancer cells." (PMID 33879256, 2021). "Interestingly, although METTL3 and METTL14 seem to play completely opposite roles in HCC progression, which may not be the case in other tumors, such as downregulated METTL3 expression detected in approximately 70% of endometrial cancers, which may be related to tumor heterogeneity." (PMID 35223847, 2022).
osteoporosis (41 papers, 2018 to 2025). A condition of reduced bone mass, with decreased cortical thickness and a decrease in the number and size of the trabeculae of cancellous bone (but normal chemical composition), resulting in increased fracture incidence. "In bone, the estrogen-deficiency induced osteoporosis is the result of Mettl3 downregulation which leads to decreased mRNA stability of Runx2 and therefore impaired osteoblast differentiation." (PMID 40180675, 2025). "The BMMSC-specific deletion of Mettl3 in mice causes osteoporosis, increased marrow adiposity, and reduced osteogenic differentiation." (PMID 38052820, 2023). "METTL3 activity seems to be essential also for osteogenicdifferentiation.Indeed, METTL3 deletion in mesenchymal stem cells (MSCs) was associatedwith impaired osteogenic potential and osteoporosis." (PMID 36692498, 2023). "For example, Mettl3 overexpression in BMSCs protected mice from estrogen deficiency-induced osteoporosis." (PMID 36650131, 2023). "Silencing METTL3 suppressed the osteogenic differentiation of BMSCs, leading to impaired bone formation and bone marrow fat accumulation, and METTL3 overexpression alleviated estrogen deficiency-caused osteoporosis." (PMID 34645714, 2021). "And overexpression of METTL3 in BMSCs protects mice from osteoporosis caused by estrogen deficiency." (PMID 34645714, 2021). "Conversely, METTL3 overexpression in BMSCs protected the mice from estrogen deficiency-induced osteoporosis." (PMID 31998240, 2019). "In a study by Wuet al., animal experiments were conducted and confirmed that Mettl3 deficiency in bone marrow MSCs leads to osteoporosis, demonstrating to some extent the feasibility of targeting m6A to regulate bone formation-related cells for the treatment of osteoporosis." (PMID 37394885, 2023). "A recent study has found that high glucose and high fat-induced ferroptosis in osteoblasts may be the main cause of osteoporosis in DM by activating the methyltransferase-like 3 (METTL3)/Apoptosis signal-regulating kinase 1 (ASK1)-p38 signaling pathway." (PMID 38076182, 2023). "Downregulation of METTL3 caused the decline in bone formation and overexpressed METTL3 could partially rescue the feature of osteoporosis such as reduction in bone formation." (PMID 35718942, 2022). "After the study, it was found that knockdown Mettl3 mice BMSCs had poor osteogenic differentiation ability, which led to a decrease in osteoblasts and osteocytes, bone loss, and even the development of osteoporosis." (PMID 35846376, 2022). "The up-regulation of METTL3 in MSCs can prevent estrogen deficiency-induced osteoporosis." (PMID 34094986, 2021). "Moreover, Mettl3 overexpression in MSCs protects the mice from estrogen deficiency-induced osteoporosis." (PMID 30429466, 2018). "In addition, Mettl3 overexpression protects mice from estrogen deficiency-induced osteoporosis." (PMID 37533592, 2023). "The upregulation of METTL3 in osteoporosis increases m6A modifications on Atp6v0d2, facilitating its recognition by YTHDF2, which reduces its stability." (PMID 39897026, 2025). "In mice, a conditional knockout study of Mettl3 showed the development osteoporosis-like symptoms, characterized by diminished bone formation and reduced osteogenic differentiation." (PMID 40180675, 2025). "Decreased methylation levels and lower expression of METTL3/METTL14 were revealed in osteoporosis-BMSCs than in BMSCs from the control group." (PMID 38665846, 2024). "Our research showed significantly reduced m6A modification levels and markedly downregulated METTL3 expression levels in senile osteoporosis patients." (PMID 38538596, 2024). "Mouse osteoblasts were specifically targeted for METTL3 overexpression, which effectively delayed the age-related reduction of bone formation and inhibited the progression of senile osteoporosis." (PMID 38538596, 2024).
osteoporosis (continued). "In rat BMSCs isolated from osteoporosis models, overexpressing METTL3 restored the osteogenic ability by activating the Wnt/β-catenin signaling pathway and subsequently increased the expression of β-catenin, RUNX2, OPN, P-Gsk-3β, and Lef1." (PMID 38665846, 2024). "Chi3l1 levels are increased in osteoporosis, which is regulated by enhancing METTL3-mediated m6A methylation of Chi3l1." (PMID 39769202, 2024). "This study discovered a reduction in m6A modification and methyltransferase-like 3 (METTL3) expression in patients with senile osteoporosis." (PMID 38538596, 2024). "And EGR1 positively promotes osteoclastogenesis in osteoporosis by increasing METTL3 and CHI3L1 levels." (PMID 38355483, 2024). "In summary, our study provides new evidence of the essential role of METTL3 in inhibiting osteoblast senescence and the progression of senile osteoporosis." (PMID 38538596, 2024). "First, m6A modifications were found to be downregulated in bone tissues and osteoblasts in senile osteoporosis, and METTL3 was identified as the key factor behind this downregulation." (PMID 38538596, 2024). "For example, conditional knockout m6A methyltransferase Mettl3 in mice induces the pathological characteristics of osteoporosis and resulted in impaired bone formation, incompetent osteogenic differentiation potential, and increased morrow adiposity." (PMID 37533592, 2023). "The role if METTL3 in osteoporosis was attributable to its function as a ceRNA that upregulated BMPR1B via sponging miR-144-3p." (PMID 37047394, 2023). "Recent research has investigated the role of methyltransferase-like 3 (METTL3) in progression of osteoporosis." (PMID 37047394, 2023). "METTL3 depletion in BMSCs impaired osteogenic differentiation, while METTL3 overexpression partly abrogated the induction of osteoporosis in mice." (PMID 36527141, 2022). "Firstly, the expression levels of METTL3 and m6A methylation are significantly decreased in both osteoporosis patients and mouse models." (PMID 35718942, 2022). "Administration with piR-36741 mimic attenuated ovariectomy-induced osteoporosis in mice through METTL3-mediated m6A methylation of BMP2 transcripts." (PMID 35634512, 2022). "A recent study has consecutively revealed that knockout of METTL3 in BMSCs of mice disrupts cell fate and results in osteoporosis pathological phenotypes, uncovering an efficient and specific regulation of METTL3 mediated m6A on MSCs." (PMID 34496349, 2021). "In conclusion, piRNA-36741 overexpression promoted osteogenic differentiation of BMSCs and mitigated ovariectomy-induced osteoporosis through METTL3-mediated m6A methylation of BMP2 transcripts." (PMID 34645714, 2021). "Recent released studies has suggested that m6A modification and its regulatory enzymes such as FTO, METTL3 are the key factors for osteoporosis." (PMID 32110378, 2020). "Conditional knockout of the m6A methyltransferase METTL3 in BMSCs induced pathological features of osteoporosis in mice and resulted in impaired bone formation, incompetent osteogenic differentiation potential, and increased marrow adiposity." (PMID 31998240, 2019). "Here the authors show that the m6A methyltransferase Mettl3 ensures translational efficiency of the mesenchymal stem cell lineage allocator Pth1r, promoting osteogenesis and protecting from osteoporosis." (PMID 30429466, 2018). "Overall, the skeletal manifestations of Mettl3 conditional knockout mice resemble the pathological phenotypes of osteoporosis, implying a lineage allocation disorder in MSCs with low m6A methylation level." (PMID 30429466, 2018). "Here we show that conditional knockout of the m6A methyltransferase Mettl3 in bone marrow mesenchymal stem cells (MSCs) induces pathological features of osteoporosis in mice." (PMID 30429466, 2018). "Current research has focused on inhibitors; however, it is important to note that the upregulation of METTL3 may also contribute to the treatment of osteoporosis." (PMID 39779466, 2025).